VPS26A (VPS26 retromer complex component A)
Description:
Acts as a component of the retromer cargo-selective complex (CSC). The CSC is believed to be the core functional component of retromer or respective retromer complex variants acting to prevent missorting of selected transmembrane cargo proteins into the lysosomal degradation pathway. The recruitment of the CSC to the endosomal membrane involves RAB7A and SNX3. The SNX-BAR retromer mediates retrograde transport of cargo proteins from endosomes to the trans-Golgi network (TGN) and is involved in endosome-to-plasma membrane transport for cargo protein recycling. The SNX3-retromer mediates the retrograde endosome-to-TGN transport of WLS distinct from the SNX-BAR retromer pathway. The SNX27-retromer is believed to be involved in endosome-to-plasma membrane trafficking and recycling of a broad spectrum of cargo proteins (Probable). The CSC seems to act as recruitment hub for other proteins, such as the WASH complex and TBC1D5 (Probable). Required for retrograde transport of lysosomal enzyme receptor IGF2R. Required to regulate transcytosis of the polymeric immunoglobulin receptor (pIgR-pIgA). Required for the endosomal localization of WASHC2A (indicative for the WASH complex). Required for the endosomal localization of TBC1D5. Mediates retromer cargo recognition of SORL1 and is involved in trafficking of SORL1 implicated in sorting and processing of APP. Involved in retromer-independent lysosomal sorting of F2R. Involved in recycling of ADRB2. Enhances the affinity of SNX27 for PDZ-binding motifs in cargo proteins (By similarity).
Synonyms: VPS26; Hbeta58; PEP8A; HB58
Tractability: Small molecule: a structure with a bound ligand is known; it has a binding pocket of medium quality. Antibody: UniProt places it where antibodies can reach, with high confidence. PROTAC: ubiquitination databases record sites on it; its protein half-life has been measured.
Gene: Protein-coding gene on chromosome 10 (69,123,512 to 69,174,412, forward strand). Ensembl gene ENSG00000122958.
Subcellular location: Cytoplasm; Endosome membrane; Early endosome
Subcellular location (Human Protein Atlas): Endosomes; Lysosomes
Pathways (Reactome):
Signal Transduction: WNT ligand biogenesis and trafficking
Gene Ontology:
Molecular function: protein binding
Biological process: endocytic recycling; retrograde transport, endosome to Golgi; intracellular protein transport; regulation of macroautophagy
Cellular component: cytoplasm; early endosome; endosome; endosome membrane; lysosome; retromer complex; retromer, cargo-selective complex; tubular endosome; vesicle; cytosol
Genetic constraint (gnomAD): Loss-of-function variants: 19 observed, 31.86 expected, observed/expected ratio (o/e) 0.6, 90% interval 0.41 to 0.88. The upper end of that interval is the gene's LOEUF score, 0.88, which puts it in group 3 of 6, group 1 being the genes least tolerant of losing a copy. Missense variants: 241 observed, 332.13 expected, observed/expected ratio (o/e) 0.73, 90% interval 0.65 to 0.81. Synonymous variants: 89 observed, 110.72 expected, observed/expected ratio (o/e) 0.8, 90% interval 0.68 to 0.96.
Homologues: Orthologues: macaque VPS26A (100% identical), chimpanzee VPS26A (99% identical), guinea pig VPS26A (99% identical), pig VPS26A (99% identical), rabbit VPS26A (99% identical), mouse Vps26a (99% identical), rat Vps26a (98% identical), tropical clawed frog vps26a (93% identical), zebrafish vps26a (91% identical), Caenorhabditis elegans vps-26 (62% identical). Paralogues in human: VPS26B (70% identical), VPS26C (21% identical).
Diseases named in the same sentence as VPS26A in open-access papers:
VPS26A is named in the same sentence as 32 diseases in open-access papers, as found by Europe PMC text mining. Sharing a sentence is not in itself a finding about the gene and the disease. The quoted sentences say what the papers report.
pancreatic cancer (2 papers, 2022 to 2023). "Knockdown of VPS26A suppressed the growth, migration and invasion abilities of pancreatic cancer cell lines while overexpression of VPS26A enhanced those in vitro through regulating the EGFR/ERK signaling pathway." (PMID 36834898, 2023). "In particular, the expression level of VPS26A in PAAD tissues was found to be much higher than that in normal pancreatic tissues (178 pancreatic tumor samples and 171 normal pancreatic samples, p-value < 2.2 × 10−16)." (PMID 36834898, 2023).
type 2 diabetes (2 papers, 2012 to 2017). "In stage 1, 88 SNPs were genotyped in 1,251 patients with type 2 diabetes, and we found that ADAMTS9-AS2 rs4607103, WFS1 rs10010131, CDKAL1 rs7756992, VPS26A rs1802295 and IDE-KIF11-HHEX rs1111875 were significantly associated with DR." (PMID 28821857, 2017).
embryonic carcinoma (1 paper, 2019). "For confirmation, another stem cell type, P19 mouse embryonic carcinoma cells (ECCs), stably transfected with short hairpin RNA (shRNA) targeting Vps26a (shVps26a-ECCs), were neurally differentiated, and the expression levels of the stemness and differentiation markers were determined." (PMID 30464227, 2019).
hepatocellular carcinoma (1 paper, 2023). A malignant tumor that arises from hepatocytes. "Vacuolar protein sorting associated protein 26 A (VPS26A) is a candidate prognosis gene for hepatocellular carcinoma, but its expression and function in PAAD remain unknown." (PMID 36834898, 2023). "VPS26A has been reported as a candidate prognosis gene for hepatocellular carcinoma; however, its expression and function in PAAD remain unclear." (PMID 36834898, 2023).
multiple system atrophy (1 paper, 2016). Multiple system atrophy (MSA) is a neurodegenerative disorder characterized by autonomic failure (cardiovascular and/or urinary), parkinsonism, cerebellar impairment and corticospinal signs with a median survival of 6-9 years. "Genetic screening on the whole VPS26a, VPS26b, and VPS29 genes have identified other VPS mutations which may produce pathogenic effects both in PD and atypical parkinsonisms, such as PSP (Progressive Supranuclear Palsy), MSA (Multiple system atrophy), and Lewy body dementia (LBD)." (PMID 27932943, 2016).
psoriasis (1 paper, 2024). An autoimmune condition characterized by red, well-delineated plaques with silvery scales that are usually on the extensor surfaces and scalp. "Furthermore, this study marks the initial identification of several proteins—MAPRE1, SWAP70, VPS26A, BRD2, and B3GNT2—as potentially contributing factors in the pathogenesis of psoriasis." (PMID 39883516, 2024).
teratoma (1 paper, 2019). A non-seminomatous germ cell tumor characterized by the presence of various tissues which correspond to the different germinal layers (endoderm, mesoderm, and ectoderm). "Moreover, transcription levels of the stemness markers in Vps26a-/- teratomas were maintained at a higher level than those in WT teratomas, indicating that Vps26a-/- ESCs exhibit differentiation resistance during teratoma formation." (PMID 30464227, 2019).
tumor (9 papers, 2014 to 2025). "Conversely, a negative correlation was noted between gamma delta T cells, NK cells, Tfh cells, MAIT cells, and cytotoxic T cells, suggesting that VPS26A expression is closely linked to the tumor immune microenvironment in LIHC." (PMID 40731912, 2025). "Further analysis indicated that VPS26A expression was associated with the methylation levels of specific probes distributed across both the promoter and exon regions in tumor and normal tissues." (PMID 40731912, 2025). "The elevated VPS26A expression was positively correlated with the histological type, tumor stage simplified, smoking status and tumor mutational burden score, and negatively related to the prognosis of PAAD patients." (PMID 36834898, 2023). "In addition, the expression level of VPS26A was positively correlated with tumor mutational burden (TMB) score (r = 0.23, p = 0.003) in PAAD." (PMID 36834898, 2023). "Collectively, these findings reveal that VPS26A is consistently overexpressed in LIHC and is functionally associated with tumor progression, immune regulation, and therapeutic responsiveness." (PMID 40731912, 2025). "This study provides novel insights into the molecular mechanisms underlying LIHC progression, and highlights the multifaceted role of VPS26A in tumor biology." (PMID 40731912, 2025). "LIHC demonstrated marked upregulation of VPS26A protein expression, as indicated by strong cytoplasmic staining in tumor cells." (PMID 40731912, 2025). "VPS26A expression was found to correlate significantly with several clinical parameters, including primary tumor; tumor stages I, II, and III; tumor grades I, II, III, and IV; and histological subtypes." (PMID 40731912, 2025). "VPS26A expression was notably affected by clinical parameters such as the primary tumor, race (Asian), age group (41–60 and 61–80 years), tumor stage (I, II, and III), and tumor grade (II, III, and IV)." (PMID 40731912, 2025). "Although VPS26A has been shown to regulate cell proliferation, migration, and invasive ability in a variety of tumors, thereby promoting tumor progression, its specific function in GC needs to be further investigated." (PMID 40191191, 2025). "VPS26A mRNA expression was correlated with the histological type, number pack year smoked, tumor stage simplified, cigarettes per day and overall survival (OS)." (PMID 36834898, 2023). "The analysis of the transposon integration sites identified several candidate genes, of which Man1a1, Pkp4, Rab10, Rasa1, Trps1, Vps26a, Xpnpep3 and Znf326 accelerated tumor growth, whereas the silencing of R3hcc1l reduced tumor growth." (PMID 36497409, 2022). "We verified the expression of ADARB1, ETF1, NRP1, and VPS26A in GBM tumor tissues and normal brain tissues through GEPIA." (PMID 32469390, 2020). "We propose that VPS26A functions as a regulator of tumor progression in LIHC, and may serve as a valuable biomarker for prognosis and therapeutic response." (PMID 40731912, 2025). "Given the crucial role of intracellular trafficking in oncogenic signaling, immune evasion, and therapeutic resistance, elucidating the role of VPS26A in cancer may offer novel insights into tumor biology and help identify new targets for intervention." (PMID 40731912, 2025). "Its association with immunosuppressive tumor-infiltrating immune cells and promoter hypomethylation suggests that VPS26A may play a role in fostering an immune-tolerant tumor microenvironment." (PMID 40731912, 2025). "These interactions provide novel insights into the chemically modifiable characteristics of VPS26A, suggesting its potential involvement in broader regulatory networks that may influence tumor progression and treatment responses in LIHC." (PMID 40731912, 2025). "To elucidate the biological role of VPS26A in LIHC, we investigated its association with tumor-infiltrating immune cells and identified distinct immunological patterns, suggesting its involvement in modulating the tumor immune microenvironment." (PMID 40731912, 2025).
tumor (continued). "Furthermore, VPS26A expression was found to correlate with the histological type and tumor stage simplified in LIHC." (PMID 40731912, 2025). "Furthermore, VPS26A expression was found to be correlated with the histological type and tumor stage simplified in PAAD." (PMID 36834898, 2023). "Using the PAAD data from the Clinical Proteomic Tumor Analysis Consortium (CPTAC) database, we found that the protein expression level of VPS26A in tumor tissues is significantly higher than that in normal tissues." (PMID 36834898, 2023).
cancer (3 papers, 2021 to 2025). A tumor composed of atypical neoplastic, often pleomorphic cells that invade other tissues. "The overexpression observed in these databases demonstrates the potential importance of VPS26A as a pan-cancer biomarker with diagnostic and prognostic significance in LIHC." (PMID 40731912, 2025). "Then, we obtained the Lollipop charts related to the mutations of the VPS26A gene in the TCGA pan-cancer cohort." (PMID 36834898, 2023). "Moreover, analysis across various cancer types further supported the association between elevated VPS26A expression and adverse survival outcomes." (PMID 40731912, 2025). "Aprevious study indicated that VPS26A might be associated with cancer prognosis." (PMID 33351066, 2021). "Collectively, these findings suggest that VPS26A is an integral component of a complex network of signaling and trafficking proteins critical for cancer progression, inflammation, and cellular metabolism." (PMID 40731912, 2025). "Using an integrative bioinformatics approach, we evaluated VPS26A expression across various cancer types and confirmed its significant upregulation in LIHC at both mRNA and protein levels." (PMID 40731912, 2025). "To explore the expression profile of VPS26A across various cancer types, we performed a pan-cancer analysis using RNA sequencing data from TCGA via the TIMER database." (PMID 40731912, 2025). "VPS26A was found to be integrated into a highly interconnected signaling network comprising proteins in cancer progression, immune regulation, and cellular metabolism." (PMID 40731912, 2025). "We also analyzed the somatic copy number alteration (SCNA) profile of VPS26A in pan-cancer and found a certain level of arm-level deletion and arm-level gain in PAAD." (PMID 36834898, 2023). "In almost all cancer types, VPS26A expression was positively correlated to the infiltration of neutrophils and negatively correlated to that of NK T cells in all of the algorithms." (PMID 36834898, 2023). "We further analyzed the relationship between VPS26A expression and immune cell infiltration in pan-cancer using multiple algorithms." (PMID 36834898, 2023). "Few studies have investigated the involvement of VPS26A in cancer development." (PMID 40731912, 2025). "Although alterations in other retromer components, such as VPS35 and VPS29, have been associated with cancer and neurodegenerative diseases, the role of VPS26A in malignancies, particularly LIHC, has not been thoroughly examined." (PMID 40731912, 2025). "Notably, in the GSE28735 dataset, the paired analysis of VPS26A mRNA expression in cancer tissue and the paired paracancerous tissues of the same PAAD patient strongly supported this conclusion (n = 45)." (PMID 36834898, 2023). "Gene functional enrichment analysis further indicated that the co-expressed genes of VPS26A might be related to the regulation of cell adhesion, actin cytoskeleton and the Hippo signaling pathway and others, which have been reported to contribute to cancer growth and metastasis." (PMID 36834898, 2023). "The genomic alteration analysis of VPS26A showed that alterations to the VPS26A gene were not universal in pan-cancer." (PMID 36834898, 2023). "In summary, among the prognostic genes we screened, the potential relationship amongBIRC5, HMOX1, and VEGFA in HCC prognosis had been reported previously, while VPS35might be a newly identified oncogene of HCC, and further, VPS26A and PRKCD were alsofound to have roles related to cancer." (PMID 33351066, 2021). "However, comprehensive investigations of the expression patterns, prognostic significance, immune microenvironment associations, epigenetic regulation, and functional networks of VPS26A in cancer remain lacking." (PMID 40731912, 2025).
infection (2 papers, 2020 to 2022). The state of being infected such as from the introduction of a foreign agent such as serum, vaccine, antigenic substance or organism. "Thus, we decided to investigate the role of the retromer complex in trans-infection using siRNA targeting key components, VPS26A and VPS35, of the retromer complex." (PMID 32075937, 2020).
VPS26A also shares sentences with these, for which no sentence is quoted: Alzheimer disease (6 papers); neurodegenerative disease (3); Obesity (2); pancreatic adenocarcinoma (2); Parkinson’s (2); Ataxia (1); bladder cancer (1); brain tumor (1); Cognitive impairment (1); diabetes (1); esophageal carcinoma (1); glioblastoma multiforme (1); head and neck squamous cell carcinoma (1); HIV-1 infection (1); kidney chromophobe (1); lentivirus infection (1); lung squamous cell carcinoma (1); prostate adenocarcinoma (1); rectal adenocarcinoma (1); retinal degeneration (1); thyroid carcinoma (1); uterine corpus endometrial carcinoma (1).